EGFR (epidermal growth factor receptor)
Diseases named in the same sentence as EGFR in open-access papers (continued):
Sharing a sentence is not in itself a finding about the gene and the disease.
cancer (continued). "In this scenario, to overcome acquired cancer resistance to first generation anti-EGFR mAbs, such as cetuximab or panitumumab novel mAbs that could more efficiently block EGFR signaling." (PMID 29137301, 2017). "Epidermal growth factor receptor (EGFR) of CRC cells is a crucial target for cancer therapy." (PMID 28852020, 2017). "Hyaluronan–CD44 interaction up-regulates EMMPRIN, a molecule belonging to the Ig superfamily present on the plasma membrane of normal and cancer cells and induces breast epithelial cell invasiveness by promoting EGFR signalling and assembly with EGFR and CD44 in lipid raft like domains." (PMID 28465354, 2017). "However, to date, cancer heterogeneity and the drug resistance greatly limit the usefulness of anti-EGFR agents." (PMID 28430586, 2017). "Finally, several different review articles have been published on the role of EGFR in the pathogenesis of human carcinoma and it was proposed as a potential novel therapeutic target." (PMID 29020948, 2017). "However, EGFR-PPARGC1A fusion gene in A431 is characterized by its presence in epithelial carcinoma and the frameshift of its 3′ fusion partner." (PMID 28978917, 2017). "Additionally, PSMD3 from our CARBO model was identified as differentially expressed in human cancer cell lines that were sensitive or resistant to the EGFR inhibitor lapatanib." (PMID 26892349, 2016). "EGFR activation in cancer has been shown to increase various transcription factors that may affect the type and the duration of EGFR signaling." (PMID 27494858, 2016). "The G protein-coupled receptor (GPCR) agonists (such as lysophosphatidic acid, thrombin, endothelin-1, and angiotensin II) can also promote the EGFR signaling via transactivation, a biological process naturally occurring in both cancer and cardiovascular diseases." (PMID 27104520, 2016). "Though overexpression of epidermal growth factor receptor (EGFR) in several forms of cancer is considered to be an important prognostic biomarker related to poor prognosis, clear correlations between biomarker assays and patient management have been difficult to establish." (PMID 27388754, 2016). "Epidermal growth factor receptor and its ligands are frequently up‐regulated in human cancers." (PMID 26762600, 2016). "It was hypothesized that some clones within a resistant cancer remained sensitive to EGFR inhibition and that withdrawal of the TKI could “let loose” these clones with resultant adverse outcomes." (PMID 28149837, 2016). "Activation of EGFR is thought to regulate the processes of metastasis and cancer cell survival." (PMID 26958807, 2016). "The ability to use a single therapeutic for cancers expressing either wild type EGFR or EGFRvIII broadly expands the range of cancers for which these molecules could become therapeutic options someday." (PMID 27153091, 2016). "Several lines of recent evidence suggest that immune responses to EGFR might be useful as a marker and/or target for cancer therapy." (PMID 27833557, 2016). "NID2 re-expression in cancer cells revealed attenuated EGFR activity." (PMID 27793011, 2016). "Although no study has shown that combined pharmacotherapy increases the sensitivity of SCCB to radiotherapy, studies of other cancers showed that a cisplatin-based regimen with an anti-EGFR agent may radiosensitize squamous cancer cells." (PMID 26863453, 2016). "However, little is known about EGFR and NeuGcGM3 co-expression in cancer patients and their therapeutic implications." (PMID 27449755, 2016). "In addition, the stimulation of cancer-related receptors, such as the epidermal growth factor receptor (EGFR), can induce the generation of macropinocytosis." (PMID 27517152, 2016). "However, inhibitors that target canonical, ligand-stimulated EGFR signaling have proven to be largely ineffective in treating many EGFR-dependent cancers with the exception of non-small cell lung cancers (NSCLC) carrying activating mutations in EGFR." (PMID 27542271, 2016).
cancer (continued). "While Src plays important role in cancer independent its role in EGFR transactivation and has been targeted for cancer therapy, the identification of its role in EGFR transactivation may provide an additional reason to target Src for cancer therapy." (PMID 26771606, 2016). "Tyrosine kinase inhibitors (TKIs) directed against EGFR, such as gefitinib or erlotinib, are among the first molecular-targeted agents to be approved in the US and other countries, for the treatment of various human cancers with over-expressed or over-activated EGFR." (PMID 27376254, 2016). "Activation of the EGFR signalling pathway resulted in cell proliferation, anti-apoptosis, angiogenesis, metastasis, and chemoresistance to gemcitabine and EGFR-TKIs and promoted the activity of stem cells in various cancers." (PMID 27596051, 2016). "Thus, autophagy regulation represents a promising approach for improving the efficiency of EGFR-TKI in the treatment of cancer patients." (PMID 27666552, 2016). "Recent experiments have identified the existence of such populations of “cancer persister cells” in a cell line of EGFR+ nonsmall cell lung cancer, indicating that bet-hedging may play a role in the emergence of cancer drug resistance." (PMID 27770034, 2016). "Open remains whether this EMF pattern impacts on cancer cell survival upon treatment with radiotherapy, chemotherapy and the molecular-targeted agent Cetuximab inhibiting the epidermal growth factor receptor." (PMID 27959944, 2016). "The EGFR pathway is frequently dysregulated in human cancer, and EGFR activation may regulate the immunological visibility of stressed pre-malignant cells." (PMID 27703456, 2016). "Ad-anti-EGFR inhibited cancer cell growth by reducing activation of EGFR, ERK and MEK in vitro." (PMID 27058423, 2016). "Overexpression of EGFR has been shown to promote cancer cell motility and invasion." (PMID 27830833, 2016). "In contrast, the EGFR mRNA and protein levels were consistently higher in the cancer tissues." (PMID 27057632, 2016). "Because anti-cancer drug-resistance is related with the enhanced cell motility, it is plausible that EGFR may regulate the response to anti-cancer drugs." (PMID 26863629, 2016). "Although several EGFR‐specific inhibitors and antibody have been used in clinical cancer therapy, the extent to which inhibition of these molecules is clinically applicable to the prevention and treatment of cardiac diseases in human patient remains to be determined." (PMID 26762600, 2016). "EGFR is a cell membrane receptor with intrinsic protein tyrosine kinase activity that has been the subject of rigorous investigation in view of its involvement in several human cancers and its potential as a target of therapy." (PMID 27830833, 2016). "In light of this, the observations that sEGFR levels decrease in cancer patients support the hypothesis that these soluble forms of EGFR have a physiological and protective role against cancer." (PMID 27104520, 2016). "Our research demonstrated that asporin might promote cancer cell invasion by targeting the EGFR/Src/cortactin signaling pathway." (PMID 27705916, 2016). "Epidermal Growth Factor Receptor (EGFR) is an attractive target in many cancer cells." (PMID 27374619, 2016). "This suggests a role of mitochondrial EGFR in cancer progression." (PMID 27087918, 2016). "Such cross-talk between integrins and EGFR has been hypothesized to play a critical role in cancer progression." (PMID 26850110, 2016). "The absence of T-type ctDNA upon initiation of chemotherapy might be explained either by cancer dormancy or due to complete elimination of the corresponding cancer cells by the preceding EGFR-TKI treatment." (PMID 27934896, 2016). "In particular, as observed in SCAC, high EGFR expression and a low percentage of RAS mutations have also been reported in HNSCC23, 24, 25, and this was the basic starting point for research into mAb anti-EGFRs in this type of cancer." (PMID 27886225, 2016).
cancer (continued). "Thus, the EGFR is becoming a dominant target for scientists attempting to understand cancer and for clinicians attempting to improve cancer treatment, including using specific tyrosine kinase inhibitors (TKI) and monoclonal antibodies specific targeting EGFR." (PMID 26918608, 2016). "Immunotoxins targeting wild type EGFR may be ideal for treating cancers with EGFR amplification or overexpression, but some EGFR-driven cancers rely upon expression of EGFRvIII, a truncated form of EGFR." (PMID 27153091, 2016). "Moreover, it was also reported that the capping with the EGFR antibody CET resulted in specific targeting to cancer cells with high EGFR level." (PMID 27151505, 2016). "Furthermore, the causal and contextual roles of the EGFR-PI3K-AKT-mTOR, EGFR-Ras and EGFR-Stat3 signaling, and mitochondrial homeostasis in this intricate interplay between EGFR and autophagy in regulating cancer progression would have to be considered." (PMID 30370422, 2016). "111In-labeled EGF-Au NP hold promise as a new approach to the treatment of EGFR-positive cancers." (PMID 26999580, 2016). "Therefore, this study uses bioinformatics algorithms to delineate interactions resulting from EGFR inhibitor use in cancer cells with these genetic alterations." (PMID 27650546, 2016). "The EGFR has been shown to be a regulator of “stemness” in cancer cells." (PMID 26867148, 2016). "Therefore, targeting EGFR remains a challenge in anti-cancer therapy and further elucidation of the complex mechanisms underlying activation of the receptor by chemically synthesized small molecules is required." (PMID 26883293, 2016). "Epidermal growth factor receptor (EGFR) plays important roles in human cancer." (PMID 27527130, 2016). "The results indicate that stress-induced endocytosis and degradation are two independent events and suggest stress signaling may utilize a double-secure mechanism to down-regulate cell surface EGFR in cancer cells." (PMID 27034618, 2016). "Therefore, targeting lipid metabolism combined with EGFR-TKIs is potentially a novel therapeutic strategies for cancer treatment." (PMID 27447558, 2016). "Since these mechanisms are likely to be instrumental to the anti-cancer efficacy of EGFR-, Raf- and MEK-directed inhibitors, improvement in the targeted delivery of these drugs to malignant cells represents a valid strategy in the effort to limit their off target toxicity." (PMID 27322144, 2016). "In contrast, this pathway might be redundant or irrelevant, perhaps due to a low level of activation by AREG and EREG, in cancer cells, thus rendering the blockade of EGFR by cetuximab ineffective." (PMID 27344184, 2016). "Utilizing the extracellular region common to both truncated EGFRvIII and wild type EGFR as an antigen, antibodies that can bind both EGFRvIII and wild-type EGFR are being used as the basis of bi-specific immunotoxins to target diverse cancers with either EGFR amplification or EGFRvIII expression." (PMID 27153091, 2016). "Thus, for effective clinical cancer treatment using anti-EGFR regimen, it is critical that we understand molecular details of the nexus between the EGFR-signaling and autophagy." (PMID 30370422, 2016). "It was reported that A5 downregulated the EGFR protein levels in cancer cells." (PMID 27376254, 2016). "An EGFR specific inhibitor, gefitinib, is successfully used for treating several cancers." (PMID 28053990, 2016). "This approach could be an effective strategy for treating EGFR T790M-positive cancers that have a decreased apoptotic response to EGFR inhibition." (PMID 28149837, 2016). "GALNT2 can also modify the activity of EGFR or the IGF-1 receptor in cancer." (PMID 26848976, 2016). "Loss of MIR-491 could regulate IGFBP2, CDK6 and EGFR proliferative pathways, by which the propagation of GBM cancer stem cells was inhibited." (PMID 27905892, 2016).
cancer (continued). "Previous studies show that NR4A1 acts as a coactivator of genes with GC-rich promoters (pathway 3) that play a role in cancer cell proliferation and survival, and these include survivin, bcl-2, cyclin D1, epidermal growth factor receptor (EGFR) and the oncogene cMyc." (PMID 27144436, 2016). "We next examined the effect of EGFR on the response to anti-cancer drugs." (PMID 26863629, 2016). "In pathological conditions such as cancer, EGFR and VEGFR signaling are main targets to inhibit." (PMID 27243144, 2016). "Epidermal growth factor receptor (EGFR) represents a promising new therapeutic target in cancer." (PMID 27313893, 2016). "The aberrant activation of the EGFR is strictly related with cancer development and progression." (PMID 27104520, 2016). "Interestingly, this concentration has been demonstrated to completely inhibit EGFR phosphorylation in other cancer models." (PMID 26788073, 2016). "Indeed cancer therapies such as antibodies targeting EGFR and HER2 [for example] as well as inhibitors of estrogen receptor activity are extensively used in the clinic." (PMID 27768738, 2016). "The selective EGFR-targeting and clinical benefit of lapatinib in cancer progression and metastasis indicate that lapatinib might be a candidate therapeutic drug for TNBC." (PMID 26824320, 2016). "The down-regulation of EGFR or HER2 enhanced the sensitivity to anti-cancer drugs." (PMID 26863629, 2016). "It has been known that cAMP signaling can transactivate EGFR in many types of cancer cells." (PMID 27273257, 2016). "Bacterial lectin PFL exhibited novel anti-cancer characteristics as follows: 1) PFL had a cytotoxic effect on cancer cells, inducing significant autophagy, which was triggered by direct binding of PFL to cell surface integrin/EGFR, causing internalization." (PMID 26850110, 2016). "It is well known that EGFR is a rational target for cancer therapy." (PMID 27542271, 2016). "Epidermal growth factor receptor (EGFR) plays an important role in cancer development." (PMID 27014908, 2016). "Also, under conditions of anti-EGFR therapy in cancer cells, feedback activation of the pro-survival signaling by activation of other growth factor receptors can occur." (PMID 30370422, 2016). "Thus, EGFR aberrant activity and its signaling complexity are crucial in the pathogenesis of human cancer." (PMID 27732953, 2016). "For example, expression of EGFR was decreased in the eight cancer cell lines after transfection of siSp1, siSp3 and siSp4 and expression of all of gene products (EGFR, survivin, bcl-2 and VEGF) were decreased in cells transfected with siSp3 and siSp4 but variable responses were observed for siSp1." (PMID 26967243, 2016). "In this study, we performed mutational profiling in a cohort of 83 NSCLC patients with TKI-sensitizing EGFR mutations at diagnosis and acquired resistance to three different first-generation EGFR TKIs using targeted next generation sequencing (NGS) of 416 cancer-related genes." (PMID 27528220, 2016). "Taken together, Stat3 activation might emerge as an alternative oncogenic bypass and drive cancer cells to escape the EGFR signaling or the TKI suppression." (PMID 27419630, 2016). "For example, EGFR is one of the critical targets of EGCG in the repression of cancer proliferation." (PMID 27669218, 2016). "However, EGFR induces and suppresses autophagy in cancer cells, and inhibiting EGFR-signaling also promotes autophagy." (PMID 30370422, 2016). "The regulatory role of miR-26a in cancer resistance to EGFR-TKIs may necessarily suggest its involvement in EGFR signaling or in mediating a crosstalk of other signal pathways with EGFR signaling." (PMID 27285768, 2016). "However, most cancers that have initial huge response to EGFR-TKIs eventually acquire drug resistance." (PMID 27270313, 2016). "The involvement of miR-26a in cancer cell resistance to EGFR-targeted TKIs may prompt a possible regulation of miR-26a expression by EGFR signal pathway." (PMID 27285768, 2016).
cancer (continued). "When coupled with the observed overexpression of FAM83 members in diverse cancers, we propose that the potentially large therapeutic window may provide new methods to target EGFR/RAS-driven tumors." (PMID 27221039, 2016). "Anti-cancer strategies based on molecules targeting crucial enzymes involved in tumoral aerobic glycolysis, may help to overcome anti-EGFR resistance in cancer improving the response of those patients to conventional chemotherapy." (PMID 27323830, 2016). "Indeed, several “glycosylation-only” EGFR-targeting therapies have recently been judged to be ineffective as cancer therapies." (PMID 27613843, 2016). "Monoclonal antibody against EGFR (cetuximab) has been used in treatment of several cancers." (PMID 27833077, 2016). "However, despite initial clinical efficacy of the anti-EGFR therapy in cancer treatment, long-term attempt to mute the cancer boosting effects of EGFR-dependent signaling meets resistance in cancer cells." (PMID 30370422, 2016). "Using these cell lines, we next sought to determine the effect of Dsg2 on cancer cell growth and migration and whether it is mediated through EGFR and c-Src." (PMID 26918609, 2016). "Therefore, increased metastatic potential of cancer cells should be considered during treatment with EGFR TKIs in NSCLC patents." (PMID 27835594, 2016). "For cancers and precancers of the head and neck, EGFR overexpression has been frequently reported." (PMID 27598202, 2016). "Moreover, honokiol and erlotinib exhibited combinatory anti-cancer effects in 1170 cells and EGFR mutant cell lines H1650 and H1975 as demonstrated by significant abrogation of phospho-Akt and phospho-ERK expression and an increase in PARP cleavage." (PMID 27458163, 2016). "Our results show that downregulation of EGFR by MIIP suppresses cancer cell growth significantly." (PMID 26824318, 2016). "In conclusion, the mimotopes we identified from phage display peptide library could be promising candidate vaccines for active anti-EGFR immunotherapy against cancers." (PMID 27659529, 2016). "Patients with advanced cancer might develop hypomagnesemia for any of several reasons, besides anti-EGFR therapy, including decreased oral intake, surgery, platinum agents, and diarrhea." (PMID 27683640, 2016). "Therefore, EGFR inhibition has been developed as one of the most efficient strategies for cancer therapy." (PMID 27527130, 2016). "In cancers of epithelial origin, EGFR overexpression plays important role in their pathogenesis." (PMID 27875990, 2016). "However, this study definitively indicates that the primary event is the generation of H2O2, which activates EGFR in cancer cells." (PMID 26883293, 2016). "Taken together, these results suggest that HER2 may confer resistance to anti-cancer drugs by regulating the activation of EGFR and the interaction between CAGE and EGFR." (PMID 26863629, 2016). "Furthermore, EGFR is overexpressed in a variety of human cancers, such as mCRC, HNSCC, NSCLC, pancreatic cancer, glioblastoma and ovarian carcinoma." (PMID 27058423, 2016). "Aberrant activation of EGFR is involved in tumor development and progression for many cancers." (PMID 26958807, 2016). "In addition, we showed coupling to the VLPs for peptides relevant to cancer from epidermal growth factor receptor and telomerase." (PMID 26781591, 2016). "The current findings suggest a mechanism whereby CDCP1, EGFR, and Src cooperate to induce cancer aggressiveness and dissemination, and may provide a rationale for therapeutic targeting of these proteins in combination." (PMID 27495374, 2016). "This study indicates that, in addition to direct inhibition of EGFR, Mig-6 can function to inhibit Cdc42, and that dysregulation of Cdc42 pathway may play an important role in cancer metastasis." (PMID 27341132, 2016). "We identified the cancer specific transcripts EGFR and PSMA in CTCs." (PMID 27479125, 2016).